ALCAM (activated leukocyte cell adhesion molecule)
Diseases named in the same sentence as ALCAM in open-access papers (continued):
Sharing a sentence is not in itself a finding about the gene and the disease.
breast carcinoma (continued). "With respect to breast cancer, multiple studies have examined ALCAM expression at the transcript and protein levels, using a variety of methods." (PMID 20929568, 2010). "Additional correlative data in both breast cancer and melanoma cell lines showed direct relationship between the level of DNA methylation of the ALCAM promoter and ALCAM protein level." (PMID 20929568, 2010). "ALCAM mRNA is significantly reduced in primary breast tumors from patients with metastatic disease however the amount of ALCAM in breast cancer cells at metastatic sites remains poorly understood." (PMID 20929568, 2010). "The adhesion molecule ALCAM shows an altered expression in breast cancer, and has been described as a prognostic and predictive marker." (PMID 20736952, 2010). "That ALCAM expression is pro-apoptotic is contrary to its protective role against apoptosis in breast cancer cells." (PMID 21126364, 2010). "In this study, ALCAM mRNA in sixteen breast cancer cell lines derived from metastatic breast cancer tumors in the brain, lymph node and the pleural cavity, and primary breast tumors in ductal epithelium were quantified by qRT-PCR." (PMID 20929568, 2010). "In this study, the ALCAM gene was cloned and functionally characterized in a panel of breast cancer and melanoma tumor cell lines, and the influence of ALCAM on homotypic tumor cell adhesion in the pulmonary vasculature investigated." (PMID 20929568, 2010). "Notably, we found the largest difference in ALCAM gene expression between normal and respective tumor tissues in prostate and breast cancers." (PMID 35689436, 2022). "Notably, a single-chain antibody named scFv173, which recognizes ALCAM, has been shown to reduce ALCAM-mediated adhesion in breast cancer, both in vitro and in vivo." (PMID 36275816, 2022). "To address the molecular and clinical correlates of ALCAM in tissue samples, we conducted in silico analyses in published datasets comparing ALCAM mRNA levels between normal and tumor tissues in several organs and found the largest increase in prostate and breast cancers." (PMID 35689436, 2022). "Further, ALCAM is known as a protector against apoptosis and autophagy for breast cancer cells." (PMID 36547538, 2022). "Furthermore, L1CAM (L1 cell adhesion molecule) on breast cancer cells has been shown to interact with ALCAM on endothelial cells promoting tumour-endothelial interactions." (PMID 34680335, 2021). "A large amount of research has focused on ALCAM in breast cancer development and progression." (PMID 34680335, 2021). "Moreover numerous targets of miR‐148a‐3p have been identified in breast cancer, including ALCAM, NRP1, SMAD2, and SPIN1, they mainly function in regulating cell growth, metastasis, and adhesion." (PMID 32508020, 2020). "Further in-silico or functional analysis should be carried out to further investigate the effect of the identified SNP to ALCAM and RUNX1 gene as well as the crosstalk in between germline variations and somatic mutations in these breast cancer-associated genes." (PMID 31757997, 2019). "Alternative mechanism to engage with other cell types to mediate adhesion and transendothelial migration include ALCAM, which allows breast cancer cells to interact with endothelium, and NRP-1, which is involved in the interaction of ovarian cancer cells with the mesothelium." (PMID 31455004, 2019). "A recently published study presents the interactions between activated leukocyte cell adhesion molecule (ALCAM/CD166) and Gal-8, which may be important in the biology of breast cancer cells." (PMID 29320431, 2018). "So, there is possible link between ALCAM expression and the inflammatory response in breast cancer." (PMID 29315254, 2018). "Our investigation of breast cancer tissues also revealed that Wnt5a expression correlates with ALCAM expression in ER-positive breast cancers, indicating that Wnt5a-positive/ALCAM-positive breast cancers form a biologically distinct subgroup of ER-positive breast cancers." (PMID 29765514, 2018).
breast carcinoma (continued). "We examined the expression of Wnt5a and ALCAM in breast cancer specimens." (PMID 29765514, 2018). "We hypothesized that epigenetic alterations of the ALCAM gene affect ALCAM expression in relation to inflammation and contribute to the progression of breast cancer." (PMID 29315254, 2018). "Studies have shown that serum ALCAM levels significantly increased in patients with breast cancer and can be used as a prognostic and predictive indicator; the expression level of ALCAM in the urine of patients with bladder cancer can be used as a prognostic marker for survival." (PMID 29375378, 2017). "However, it has yet to be demonstrated that ALCAM shedding correlates with stage or outcome in breast cancer." (PMID 27894096, 2017). "Cytoplasmic overexpression of ALCAM is prognostically relevant in breast cancer." (PMID 25255861, 2014). "We tested the hypothesis that ALCAM expression would be markedly lower in cases of AA breast cancer when compared to CAU." (PMID 25255861, 2014). "The major findings are that ALCAM expression at the critically important intercellular junctions of primary breast cancer tumors is markedly lower in AA women compared to CAU women, regardless of age, histological grade, tumor size and lymph node involvement, ER/PR and HER2-neu status." (PMID 25255861, 2014). "ALCAM coalesces breast cancer cells together in homotypic interactions thus preventing interactions with neighboring endothelium, which may facilitate metastasis." (PMID 25255861, 2014). "In the current study, we tested the hypothesis that ALCAM expression is low in breast cancer tumors of AA women, and that this phenomenon may contribute to the more aggressive tumor phenotype in this patient population." (PMID 25255861, 2014). "The resulting s-ALCAM levels in our patients (mean 28.9 ng/ml) are below those reported for breast cancer patients (74 ng/ml;) and ovarian cancer patients (mean 44 ng/ml;), but slightly above those found in patients with esophageal carcinoma (mean 23.9 ng/ml;)." (PMID 22475274, 2012). "In breast cancer patients and in this study analysing cervical cancer patients, ALCAM expression in cancer tissue correlates with increased sensitivity to chemoradiation or chemotherapy which might at least partly result from its influence on apoptosis." (PMID 22475274, 2012). "In addition, shedding of ALCAM results in the increase of sALCAM in the serum of ovarian and breast cancer patients, suggesting a potential role of sALCAM as tumor biomarker, although lower levels are also present in the plasma of healthy individuals." (PMID 21364949, 2011). "There is an emerging consensus that low level ALCAM is a bad prognostic marker in breast cancer." (PMID 20929568, 2010). "5-Aza-deoxycytidine is currently in clinical use, and may be indicated to boost ALCAM expression in breast cancer, however, it also alters expression of a large number of genes." (PMID 20929568, 2010). "Therapeutic strategies that re-activate ALCAM expression in breast cancer tumors may slow-down tumor metastasis and improve survival." (PMID 20929568, 2010). "A similar mechanism may explain the marked increased in cytoplasmic ALCAM in some aggressive breast cancer tissues." (PMID 20929568, 2010). "Plausible candidates are other ALCAM isoforms, such as soluble ALCAM, which may account for the elevation of serum ALCAM in patients with breast cancer." (PMID 20929568, 2010). "By this approach, we consistently observed in all the three cohorts that the level of SPP1 and ALCAM mRNA expression enables the discrimination of good vs bad outcome in all ‘high-risk’ breast cancer patients showing low or no ESR1 and HER2 expression." (PMID 20736952, 2010). "Furthermore, preliminary results from a phase II study of praluzatamab ravtansine, an activated antibody-drug conjugate that targets ALCAM, show promising overall response rate in breast cancer patients with advanced hormone receptor–positive, HER2 negative cancer." (PMID 39840036, 2024).
breast carcinoma (continued). "Besides this, miR-148a and miR-152, by downregulating ALCAM, could reduce tamoxifen resistance in ER+ breast cancer cells." (PMID 34804971, 2021). "Markedly low expression of ALCAM at sites of cell-cell contact in primary breast cancer tumors regardless of differentiation, size and lymph node involvement may contribute to the more aggressive phenotype of breast cancer among AA women." (PMID 25255861, 2014). "Lower ALCAM expression may contribute to the aggressive phenotype of breast cancer among AA women." (PMID 25255861, 2014). "On the other hand, ALCAM expression in tumor tissue has been reported to be a potential marker for the benefit of therapeutical interventions: Previous studies of our group and others could show that ALCAM expression predicted chemotherapy response in early breast cancer and pancreatic cancer cells." (PMID 22475274, 2012). "Besides enzymatic shedding, a recent report indicates that DNA-methylation of ALCAM promoter might also be involved in surface ALCAM down-regulation and breast cancer metastases development." (PMID 21364949, 2011). "Breast cancer cells express multiple types of CAM, including PSGL-1, CD24, sLex, MUC1, CD 44, MUC1, LFA-1 (integrin αLβ2), VLA-4 (integrin α4β1), and ALCAM, whereas melanoma and lung cancer have limited CAM expression." (PMID 37190188, 2023). "Moreover, in breast cancer, the Gal8 interaction with the activated leucocyte cell adhesion molecule (ALCAM), its endothelial ligand, was identified as a mechanism responsible for ALCAM surface segregation, possibly preventing its internalization and, consequently, accelerating tumor cell spread." (PMID 37892036, 2023). "To investigate the relevance of our findings to progression of human breast cancer, we analyzed gene expression data of FN1 and two of its first-degree neighbours (PLAU and ALCAM), using data from The Cancer Genome Atlas (TCGA)." (PMID 34641959, 2021). "ALCAM, together with integrins (ITGA5), acts as a key cell surface molecule in cancer cells (melanoma and breast cancer cells, for example) and mediates the intravasation and extravasation during the metastatic process." (PMID 34680335, 2021). "Osteopontin, ALCAM, HER2 and ER mRNA expression in breast cancer tissues of 481 patients were analysed (mRNA microarray analysis, kinetic RT–PCR)." (PMID 20736952, 2010). "In breast cancer, when hormone receptors ER and Her2 are low or negative, ALCAM appears to be more prominent in its value in predicting the prognosis." (PMID 34680335, 2021). "In breast cancer cells, depletion of miR-214 can inhibit the vascular endothelial pathway of malignant cells by reducing the expression of the cell adhesion molecules ITGA5 and ALCAM." (PMID 34818353, 2021). "Analysis of gene expression data of various gene expression synthesis (GEO) datasets for breast cancer using genetic algorithms and bioinformatics tools showed that FAM134B combined with KIF2C, ALCAM, and KIF2A may identify certain subtypes of breast cancer." (PMID 33199694, 2020). "We, therefore, treated 4175-TGL and SKBR3 breast cancer, MA-2 melanoma or A549 lung cancer cells, with GL21.T, axl-148b or scr-148b molecules and evaluated ALCAM and ITGA5 protein expression levels compared to cells transfected with miR-148b precursors (pre-148b) or controls (pre-ctrl)." (PMID 32174798, 2020). "In 153 cases of ER-positive breast cancer, ALCAM was expressed in 69% of Wnt5a-positive breast cancers but only 27% of Wnt5a-negative breast cancers, a statistically significant correlation between Wnt5a and ALCAM expression (κ = 0.444; P < 0.001)." (PMID 29765514, 2018). "In a study of primary breast cancer tissues and non-neoplastic mammary tissue from the same mastectomies, we discovered that ALCAM mRNA was lower in tumors from patients who had metastases to regional lymph nodes and early mortality." (PMID 25255861, 2014).
breast carcinoma (continued). "Activated leukocyte cell adhesion molecule (ALCAM) is a bad prognostic factor of breast cancer yet it has never being studied in the AA population." (PMID 25255861, 2014). "We found that ALCAM was reduced or completely absent at intercellular junctions of most breast cancer tumors of AA women." (PMID 25255861, 2014). "Despite the significance of ALCAM in breast cancer this molecule has not previously been studied among AA women." (PMID 25255861, 2014). "Similar to the present data obtained in cervical carcinomas, ALCAM expression was not relevant for prognosis in the total breast cancer cohort." (PMID 22475274, 2012). "Our reporter gene analysis did not reveal cis-active elements in the ALCAM promoter that suppress ALCAM expression in breast cancer cell lines." (PMID 20929568, 2010). "The results of the present hypothesis-generating study show that the application of the two, in this context newly discovered, molecular markers, ALCAM and OPN, could discriminate prognostic subgroups within HER2- and ER-negative early breast cancer patients." (PMID 20736952, 2010). "These genes, including ALCAM, ARL6IP1 and CCNG2 may play a protective role in breast cancer." (PMID 37644433, 2023). "Next, we assessed the activity of various ALCAM promoter constructs truncated at -650, -800, -1000 and -1200 in breast cancer cells, and discovered no appreciable activity, even though these same cells supported high level activity of a CMV promoter driving a β-gal reporter gene (data not shown)." (PMID 20929568, 2010). "Unmethylated (U) DNA was specifically amplified in all breast cancer cell lines with detectable ALCAM expression, but not in the MDA-MB-435 cell line, which lacks endogenous ALCAM." (PMID 20929568, 2010).
melanoma (55 papers, 2008 to 2025). A malignant, usually aggressive tumor composed of atypical, neoplastic melanocytes. "ALCAM is a complex glycoprotein with 10 potential N-linked glycosylation sites that have been characterized in the melanoma cell line A375 as beta 1–6 branched oligosaccharides." (PMID 41301074, 2025). "In cutaneous melanoma, strong ALCAM staining in primary melanoma tissues is linked to short overall and disease-free survivals." (PMID 34680335, 2021). "In BLM melanoma cells, additional interactions with ALCAM, associated with high invasiveness and aggressiveness in melanomas, were also observed." (PMID 27966446, 2017). "More recently, increased ALCAM expression has been linked to a variety of cancers including pancreatic, breast, prostate, and colorectal carcinomas and melanoma." (PMID 23024593, 2012). "ALCAM protein has been associated with prognosis in melanoma, ovarian, breast, prostate, colorectal, and pancreatic cancers." (PMID 21654678, 2011). "The value of ALCAM as unfavorable prognosis marker is reported in colon, pancreas, urinary bladder, breast, and endometrial tumors, melanoma, and other types of malignancies, while the association between ALCAM strong expression and a favorable outcome is recorded in prostate cancer." (PMID 26339605, 2015). "Furthermore, knocking-out CD9 in SK-MEL-147 melanoma cells also resulted in an increased number of lysosomes, supporting the notion that the association of ALCAM and CD9 may constitute a functional unit in cancer cells." (PMID 35628559, 2022). "This interaction can increase ALCAM expression in melanoma cells, which has been found to closely correlate with the invasion of melanoma cells deeper into the dermis." (PMID 41155412, 2025). "Western blotting showed an increase in the level of another CSC marker, ALCAM, in both resistant melanoma cell lines." (PMID 39175042, 2024). "Increased CD24 expression was shown to be associated with decreased sensitivity to BRAFi in resistant melanoma cells, while elevated ALCAM levels were observed in the vemurafenib-resistant melanoma cell line." (PMID 39175042, 2024). "Several members of the IgSF, including MCAM (CD146), NCAM (CD56), ALCAM (CD166), and L1-CAM (CD171) have been associated with metastasis in several cancers such as melanoma." (PMID 34207884, 2021). "A previous study found that invasive melanoma had strong ALCAM staining compared with non-invasive and nevi tissues." (PMID 34680335, 2021). "Orso and colleagues found that inhibiting miR-214 or overexpressing miR-148b can impair melanoma metastasis, due to downregulated ALCAM and ITGA5 adhesion molecules; both of which are direct targets of miR-148b." (PMID 34943783, 2021). "Soluble ALCAM is able to antagonise the naturally occurring and natural ALCAM in melanoma cells, a contrast effect to the role of an NH2-terminally truncated, transmembrane variant (ΔN-ALCAM)." (PMID 34680335, 2021). "Subsequent studies in monocytes, endothelial cells and melanoma cells have also indicated the critical role of ALCAM in transendothelial monocyte migration, leukocyte adhesion and transmigration, and transition from local cell proliferation to tissue invasion." (PMID 32771033, 2020). "High ALCAM expression at the protein level usually correlates with a poor prognosis in melanoma, breast and colorectal cancer, among others." (PMID 31324051, 2019). "Analysis of ALCAM expression in nodal metastatic foci demonstrated that lower percentage of positive cells is closely correlated with deeper infiltration of the melanoma in the primary tumor according to Clark scale (P = 0.032)." (PMID 26134500, 2015). "Analysis of melanoma cells obtained from nodal metastatic foci showed the presence of ALCAM in 14 out of 16 cases (87.5 %)." (PMID 26134500, 2015). "Increased ALCAM expression (defined as increased IRS) in melanoma cells in primary tumor is closely correlated with higher Breslow thickness and higher Clark level (P = 0.008 and P = 0.001, respectively)." (PMID 26134500, 2015).